ERBB3 (erb-b2 receptor tyrosine kinase 3)
Diseases named in the same sentence as ERBB3 in open-access papers (continued):
Sharing a sentence is not in itself a finding about the gene and the disease.
cancer (continued). "Although most clinical focus has been on EGFR and ERBB2 due to their aberrant activation in many human malignancies, overexpression of ERBB3 often co-occurs with EGFR or ERBB2 in many types of cancers such as breast, colorectal (CRC), gastric, ovarian, and pancreatic." (PMID 34843459, 2021). "HER3, encoded by the ERBB3 gene, is broadly expressed in various types of human cancer." (PMID 33968735, 2021). "The pharmacological inhibition of ErbB3 by a monoclonal antibody sensitizes ErbB2-overexpressing cancer cells and xenografts to a tyrosine kinase inhibitor, showing that ErbB3 is an important cancer therapeutic." (PMID 34572289, 2021). "Furthermore, FLT1 of LUSC, ITGB1 of DLBC, MDM4, and CDKN1A of ACC, MAPK1, and ERBB3 of UCEC, FGFR1 of ESCA, and EREG and BCL2L1 of COAD have been strongly associated with patient survival in their respective cancers." (PMID 34079798, 2021). "The mechanisms of ErbB3-mediated resistance to anti-ErbB1/2 monoclonal antibodies, tyrosine kinase inhibitors, and hormonal therapy, and different approaches to its therapeutic targeting in cancer, have been extensively reviewed." (PMID 34572289, 2021). "Targeting ERBB3 using antibodies or small molecule inhibitors for treating cancer remains elusive." (PMID 36618440, 2021). "NRGs belong to the large family of EGF ligands, and are implicated in brain development activities by interacting with ErbB and regulating HER2, HER3, and HER4 (ERBB2, ERBB3 and ERBB4, respectively, in mice), all of which have been linked to different types of cancers in the literature." (PMID 32341755, 2020). "Previous research has highlighted the importance of ErbB3 in cancer progression." (PMID 31615015, 2019). "A total of 309 downregulated genes were common between BBI608 and YM155 treatments; these genes were associated with pathway with cancer and the ERBB signaling pathway, which included ERBB3 (HER3) and BIRC5 (Survivin), whereas BIRC5 was previously identified as an inhibitory gene of YM155." (PMID 31619200, 2019). "The EGF receptor (EGFR) (or HER) proto-oncogene family consists of four transmembrane tyrosine kinase receptors (i.e., EGFR, ErbB2, ErbB3, and ErbB4) that play a role in cancer pathogenesis and has been described as key therapeutic target in many types of cancer, including ovarian cancer." (PMID 32039018, 2019). "ErbB3 has been widely studied in cancer cells, but little is known about its role in macrophages." (PMID 29636067, 2018). "Previous studies have shown that despite the ERBB3 SNPs rs77123 and rs2229046 SNPs not having a described role in cancer susceptibility, both have been associated with alternative splicing." (PMID 30071039, 2018). "Of note, Mek inhibition is known to trigger various feedback anti-apoptotic mechanisms in cancer cells (e.g. ErbB3 upregulation) which could in principle promote their survival." (PMID 29285258, 2017). "Moreover, c-Met was found to induce ErbB3 signalling in cancer cells and the inhibition of both, c-Met and EGFR caused cancer cell death." (PMID 28417948, 2017). "Having engineered seribantumab to effectively inhibit ligand-mediated ErbB3 signaling, we turned our efforts to determining specific areas of cancer biology where ErbB3 blockade could potentially provide clinical benefit." (PMID 28725482, 2017). "In cancer cells, Necl-4 is down-regulated or dysfunctional and its inhibitory effect on the ligand-induced dimerization of ErbB3 with ErbB2 may be abolished." (PMID 28900130, 2017). "In the last years, ErbB3 signalling has gained considerable attention in cancer research." (PMID 28417948, 2017). "In brief, the current research suggests that ERBB3 is an emerging target in cancer." (PMID 29321816, 2017). "In addition, several hits, including PLK1, PRKAA1 (or AMPK), PIK3CG and ERBB3 have also been previously shown to mediate cancer cell survival and growth, independently validating the results of our screen." (PMID 27192118, 2016).
cancer (continued). "Here, we explore how spatial in-homogeneities in the plasma membrane might influence the dimerization and phosphorylation status of ErbB2 and ErbB3, two receptor tyrosine kinases that preferentially heterodimerize and are often co-expressed in cancer." (PMID 27570763, 2016). "It is worth noting that mutations in any of these three genes may affect their predictive utility in this context, however this rarely occurs in HER2+ cancers (less than 10% harbor mutations in EGFR, ERBB3, or CDKN1B)." (PMID 27035903, 2016). "HER3/ErbB3 has emerged as a new therapeutic target for cancer." (PMID 27582551, 2016). "ErbB3, a member of the ErbB family receptors, has a key role in the development and progression of several cancers, including non-small cell lung cancer (NSCLC), and in the establishment of resistance to therapies, leading to the development of anti-ErbB3 therapies." (PMID 26862736, 2016). "Moreover, in cancer cells, CDK5, ERBB2/ERBB3, and beta-catenin have been linked through another member of the beta-catenin network—the androgen receptor (AR)." (PMID 26509276, 2015). "Moreover, due to the potent activation of the PI3K survival pathway, ErbB3 plays an important role in the responsiveness of cancer cells to targeted therapies." (PMID 25630670, 2015). "Surprisingly, ERBB3+ cancer cells rarely co-localised with KI-67 nuclear staining." (PMID 26367378, 2015). "Inappropriate signaling through the epidermal growth factor receptor family (EGFR1/ERBB1, ERBB2/HER2, ERBB3/HER3, and ERBB4/HER4) of receptor tyrosine kinases leads to unregulated activation of multiple downstream signaling pathways that are linked to cancer formation and progression." (PMID 25386657, 2014). "In this review, we focus on the role of erbB3-initiated signaling in the development of cancer drug resistance and discuss the latest advances in identifying therapeutic strategies inactivating erbB3 to overcome the resistance and enhance efficacy of cancer therapeutics." (PMID 24886126, 2014). "Moreover, the activation of the ERBB3-mediated PI3K/AKT pathway renders cancer cells sensitive or resistant to ERBB inhibitors, depending on the cellular context." (PMID 24970817, 2014). "While the relationship between NRG1 expression and outcome in primary HNSCC has not been reported to our knowledge, elevated expression of ErbB3, a possible surrogate for activity, has been associated with a poor prognosis in a variety of cancer types." (PMID 25238142, 2014). "The use of ErbB3 pathway inhibitors as anti-cancer therapeutics is an area of active clinical investigation, but the range of susceptible target tumors is unknown." (PMID 25238142, 2014). "The critical downstream mediators that are responsible for erbB3 signaling-induced cancer metastasis remain unclear." (PMID 24886126, 2014). "ErbB3 is frequently co-expressed with other RTKs in cancer cells." (PMID 24886126, 2014). "It is believed that inhibition of erbB3 signaling may be required to overcome therapeutic resistance and effectively treat cancers." (PMID 24886126, 2014). "Although numerous studies have dramatically improved our understanding of the biologic features of erbB3 receptor in cancer biology, and advances have been achieved in developing Abs against erbB3 with therapeutic potential, a number of critical questions still exist." (PMID 24886126, 2014). "Indeed, advances have been made in developing erbB3-targeted therapy, and several anti-erbB3 monoclonal Abs exhibit efficacy in vivo and show promise as novel cancer therapeutics." (PMID 24886126, 2014). "For these cancers in particular, erbB3 inhibition may be required to effectively eradicate cancerous cells." (PMID 24886126, 2014). "This study revealed a dominant role of erbB3 in Akt activation and suggested that targeting this key node of the erbB signaling network might result in therapeutic benefit to cancer patients." (PMID 24886126, 2014). "ERBB3/HER3 is emerging as a molecular target for various cancers." (PMID 25400118, 2014).
cancer (continued). "ERBB3 is an emerging target for cancer therapy among the EGFR family." (PMID 24970817, 2014). "High expression of ERBB3 in certain human cancers led early to the suggestion that it could be a therapeutic target, but in some cancer cells the mesenchymal phenotype was found to lose ERBB3 expression and show resistance to EGFR inhibitors." (PMID 23135478, 2013). "It is reasonable to expect therefore, that in the next years if clinical proof-of-concept is achieved ErbB3 may become a next generation blockbuster target for cancer therapies." (PMID 22889873, 2012). "ErbB3 is one of the most particularly up-regulated genes in these cancers." (PMID 22889873, 2012). "The reactivation of ERBB3 is a prominent way by which cancers become resistant to ERBB inhibitors." (PMID 23691449, 2012). "This low interest in ErbB3 was also due to the lack of detectable mutations in cancer samples and the absence of a strongly active tyrosine kinase in its intracellular domain." (PMID 22889873, 2012). "We hypothesised that cancer-associated fibroblasts (CAF) secrete NRG-1 ligand, which in turn activates cancer cell ErbB3/AKT-mediated signalling, promoting tumourigenesis and rendering EGFR inhibition ineffective." (PMID 21792199, 2011). "Therefore, it is conceivable that the ErbB2/ErbB3 pathway can contribute to formation of malignant tumors." (PMID 22216327, 2011). "Furthermore, we observed strong correlation between Ebp1 expression and the nuclear expression of AR, Cyclin D1 and ErbB3 in both normal adjacent and cancer tissues." (PMID 19025630, 2008). "Together, these data support a key role for ErbB3 multiple types of cancer and suggest that effective inhibition of ErbB3 may be important for gaining complete therapeutic efficacy with ErbB inhibitors." (PMID 18841159, 2008). "In addition, we demonstrate that the bispecific single chain-Fv (bs-scFv) has intrinsic anti-cancer activity when measured in vitro and that the anti-ErbB3 arm of the bs-scFv is responsible for mediating this activity." (PMID 18841159, 2008). "Several ERBB3-directed monoclonal antibodies, bispecific antibodies, and emerging antibody–drug conjugates demonstrated encouraging clinical outcomes that enhance therapeutic efficacy and address resistance, particularly when combined with other anti-cancer strategies." (PMID 41465326, 2025). "Thus, cancers that harbor NRG1 fusions may be treated with specific ERBB2/HER2 or ERBB3/HER3 or pan ERBB/HER pathway inhibitors." (PMID 38369520, 2024). "Saquinavir is bound to the domain I of ERBB3 extracellular domain, which is one of the domains involved in ligand binding and inhibition may prevent activation of downstream signaling pathways that play a role in the growth of cancer cells." (PMID 38216592, 2024). "Therefore, determining whether lymph nodes have been invaded by tumors using ERBB3 as a marker could aid in the precise clinical staging of cancer." (PMID 38144565, 2023). "The epidermal growth factor receptor (EGFR) kinase family consists of four receptors [ErbB1/EGFR, ErbB2/human epidermal growth factor receptor (HER) 2, ErbB3, and ErbB4] that play a crucial role in cell proliferation, differentiation, and motility and may lead to cancer development." (PMID 36045702, 2021). "We used publically available data from the cancer cell line encyclopaedia (CCLE) database to search for mutations in EGFR, ERBB2, ERBB3, ERBB4, KRAS and BRAF that might predispose to a different response to anti-HER2 therapies or PI3K or MAPK pathway inhibition." (PMID 33933113, 2021). "Therefore, most cancer tissues probably contain anchorage-dependent ErbB3 positive cells." (PMID 31615015, 2019). "Furthermore, ErbB3/HER3 is now emerging as a novel selective therapeutic cancer target." (PMID 31632194, 2019). "Therefore, this study showed how EGFR that is transactivated by a signal within the cytoplasm may activate the ErbB3-mediated signaling pathway in cancer cells with acquired resistance to cetuximab treatment." (PMID 31615015, 2019).
cancer (continued). "By now dissecting the mechanism of action of these potent biparatopic agents as compared with ErbB2-targeting mAbs, we could elucidate compensatory responses upon blockade of ErbB2/ErbB3, which mediate adaptive resistance in ErbB2-overexpressing cancers towards mAb treatment." (PMID 27255951, 2016). "Therefore, it is believed that inhibition of ErbB3 signaling may be required to overcome therapeutic resistance and effectively treat cancers." (PMID 27609096, 2016). "This may promote the communication between ErbB-3 and c-Met in these cancer cells." (PMID 25993617, 2015). "Therefore, the modulation of ERBB3 by miR-143/145 may explain why the downregulation of miR-143/145 during breast carcinogenesis can promote cancer progression." (PMID 25248370, 2014). "Therefore, it is reasonable to consider that ErbB3 alone may play a role via its translocation to the nucleus of cancer cells, where it can target a particular gene to induce the expression of a specific oncoprotein." (PMID 25416285, 2014). "Thus, inhibition of erbB3 with blocking Ab may be a novel strategy to target Survivin for cancer treatment." (PMID 24168763, 2013). "Thus, although we did not observe the up-regulation of erbB2 at this specific time point (50 days of age), an up-regulation of erbB3 could provide ample access to a binding partner for erbB2 and provide a local environment more prone for cancer development." (PMID 19590682, 2009). "The ERBB signaling pathway, mediated by ERBB receptor tyrosine kinases (ERBB-1/EGFR, ERBB-2/HER2, ERBB-3, and ERBB-4), is crucial for cellular proliferation, survival, migration, and angiogenesis, which leads to cancer progression." (PMID 40901642, 2025). "The HER receptor family, comprising ERBB1 (EGFR), ERBB2, ERBB3, and ERBB4, plays a pivotal role in tumorigenesis and cancer progression." (PMID 40846695, 2025). "This analysis revealed upregulation of ERBB growth factor signaling to cancer cells post treatment, with increased communications received via all ERBB growth factor receptors (EGFR/ERBB1, HER2/ERBB2, HER3/ERBB3, and HER4/ERBB4)." (PMID 40341770, 2025). "The overexpression of NRG1 can activate the ERBB3/ERBB2-signaling pathway, promoting cancer cell proliferation, invasion, and metastasis." (PMID 41378303, 2025). "Addressing the dense stromal barrier, it reveals that the interaction between cancer cell NRG1 and CAF ERBB3 activates the STAT3 pathway, leading to the “ERBB3 inhibitor + stromal metalloproteinase activator” strategy." (PMID 41463034, 2025). "This variant considerably facilitated the interaction between ERBB2 and ERBB3 and triggered stronger downstream signaling cascade than the wild type ERBB2 to promote cancer cell proliferation." (PMID 39948369, 2025). "The ErbB family (EGFR, ErbB-3, and HER2) drives cancer proliferation and survival by activating Ras/MAPK, PI3K/Akt, and JAK/STAT pathways." (PMID 39138146, 2024). "The ERBB3 mutant protein (ERBB3 N418Q) blocked HIF-1α and NRF2 accumulation by inhibiting PI3K-AKT signaling activation, which resulted in the suppression of cancer growth and migration." (PMID 38424190, 2024). "Our findings offer a significant advancement in the understanding of the role of ERBB3 isoforms in RCC, highlighting their multifaceted impact on cancer biology." (PMID 38276060, 2024). "Separately, in cancers driven by EGFR, ERK provides suppressive phosphorylation of EGFR receptors, which is lost during MEK inhibition and leads to reactivation of ErbB3 and PI3K74." (PMID 39488530, 2024). "ErbB3 is involved in activating the PI3K/Akt pathway, playing a significant role in cancer development and progression." (PMID 39138146, 2024). "Consistent with a rationale for indirect targeting of ERBB3 by blocking ERBB2, responses to ERBB2 drugs have been observed in the clinic in patients with ERBB3 mutant cancers." (PMID 38806620, 2024).
cancer (continued). "The increased expression of ERBB3 in THCA, combined with its membrane localization, makes this protein an attractive target for cancer therapy." (PMID 38144565, 2023). "Next, to investigate the impact of ERBB3 on Gem resistance in PDAC patients, we performed qRT-PCR assays in clinical tissue specimens from patients with unresectable cancers obtained by EUS-FNA before initiation of treatment." (PMID 36672630, 2023). "Upon binding to neuregulin 1 (NRG1), ERBB3 preferentially dimerizes with HER2 (ERBB2), in turn inducing aggressive features in several cancer types." (PMID 35406375, 2022). "Although ERBB3 and CDK9 belong to CATH-FunFams with some propensity for side effects, these targets are still of interest and being considered for other cancers." (PMID 35035776, 2022). "Results of further gene-level analysis revealed that the SCNAs of known cancer-related genes, such as PTK6 (44.6%), ERBB3 (13.4%), PIK3CA (11.8%), and UBR5 (11.8%), were relatively frequent (eFigure 4 in Supplement 1)." (PMID 36484990, 2022). "The phosphorylated ErbB3 (pErbB3) can bind directly to PI3K, a lipid kinase that promotes proliferation, survival, adhesion, and motility of cancer cells." (PMID 35806132, 2022). "ErbB3 (HER3), a member of the HER family, is overexpressed in various cancers and plays an important role in cell proliferation and survival." (PMID 35503762, 2022). "EGFR family comprises four types of tyrosine kinase receptors, including ErbB1 (HER1), ErbB2 (HER2), ErbB3 (HER3), and ErbB4 (HER4), and it is highly expressed in cancer cells." (PMID 35565451, 2022). "In addition, ERBB3 mutations are not uncommon in many cancer types." (PMID 35406375, 2022). "These include unique cancer patient samples harboring EGFR E709K (n = 67), EGFR E928K (n = 1), ERBB2 E717K (n = 10), ERBB3 E925K (n = 7), ERBB4 E715K (n = 8), and ERBB4 E934K (n = 5) variants." (PMID 36860695, 2022). "Total ERBB3 expression in DFCI81 and DFCI161 cells increased after MET inhibition, a compensatory mechanism reported in other receptor tyrosine kinase–driven cancers treated with TKI." (PMID 34516823, 2021). "Receptor tyrosine kinases (RTK) like the ERBB receptor family, including EGFR/ERBB1, ERBB2/NEU, ERBB3, and ERBB4, are important regulators of skin homeostasis and their dysregulation often results in cancer, which makes them attractive therapeutic targets." (PMID 33786987, 2021). "In the present study, we evaluate the prevalence of KDD in ERBB family members (EGFR/EGFR, ERBB2/HER2, ERBB3/HER3, and ERBB4/HER4) across multiple types of human cancers in order to refine our understanding of KDD as an oncogenic driver." (PMID 33654076, 2021). "EGFR (also known as ErbB1 and HER1), ERBB2 (HER2/neu and HER2), ERBB3 (HER3), and ERBB4 (HER4), members of the (EGFR)/(ERBB) family, are known among the most important cancer molecular targets." (PMID 34803458, 2021). "Previous studies reported that the high level of ErbB3 and the activation of its downstream signaling including PI3K/AKT pathway and Ras/Raf pathway participated in the development and progression of cancers." (PMID 34400880, 2021). "Suppression of the expression level of Nrf2 via applying a CRISPR/Cas9 genome editing system illustrated that ERBB3 and IGF1R signaling pathway accompanied by thioredoxin and peroxiredoxin proteins play an effective role in KEAP1-mutant cancer cells." (PMID 33768092, 2021). "In cancer genomes, frequent substitutions at glycosylation sites are apparent in epidermal growth factor receptors and oncogenes EGFR and ERBB3, as well as PAPPA, a secreted protein involved in the activation of insulin-like growth factor pathways." (PMID 33834021, 2021).